FOXS1 (forkhead box S1)
Diseases named in the same sentence as FOXS1 in open-access papers (continued):
Sharing a sentence is not in itself a finding about the gene and the disease.
lentivirus infection (1 paper, 2021). Virus diseases caused by the Lentivirus genus. "Second, we investigated the changes in EMT markers when the expression of FOXS1 was changed by lentivirus infection." (PMID 34256854, 2021).
Obesity (1 paper, 2025). Accumulation of substantial excess body fat. "More sophisticated mouse diet studies are needed to understand if this is due to WAT specific FOXS1 deletion and would allow for in-depth assessment of FOXS1-dependent fibrotic WAT remodeling in diet-induced obesity." (PMID 40774386, 2025). "These processes are critical in obesity-induced WAT fibrotic WAT remodeling, suggesting that FOXS1 may mediate TGF-β1-dependent profibrotic cellular responses and promote adipocyte hypertrophy in dysfunctional WAT." (PMID 40774386, 2025).
ovarian carcinoma (1 paper, 2025). A malignant neoplasm originating from the surface ovarian epithelium. "Cinobufagin significantly inhibited the growth of Skov3 ovarian cancer cells, triple-negative breast cancer metastasis, by regulating the Forkhead Box S1 (FOXS1) gene, the CCL2/CCR2 signaling, and FAK/STAT3 signaling." (PMID 40799827, 2025).
prostate carcinoma (1 paper, 2018). A carcinoma that arises from epithelial cells of the prostate gland. "Additionally, in the 72 prostate cancer sample dataset (GEO accession: GSE56916), FOXS1 expression also strongly correlates (r = 0.439, P < 0.0001) with GLI1 expression." (PMID 30098229, 2018).
pulmonary hypertension (1 paper, 2014). Increased pressure within the pulmonary circulation due to lung or heart disorder. "Many genes are functionally related to high-altitude physiology, such as angiogenesis (RGCC), pulmonary hypertension remodeling (PLA2G12A), oxygen intake (C9ORF3), neural response (GRID1 and GRIN2B), melanin synthesis (MITF, PDGFRB and PIK3R3) and heart development (FOXS1, GAA and MYLK2)." (PMID 25270331, 2014).
renal fibrosis (1 paper, 2025). A final common manifestation of a wide variety of chronic kidney diseases characterized by glomerulosclerosis and tubulointerstitial fibrosis. "In addition, FOXS1 is an established regulator of EMT in renal fibrosis and various cancers." (PMID 40774386, 2025). "Previous studies have characterized FOXS1 as a profibrotic TGF-β-responsive TF in the liver and renal fibrosis." (PMID 40774386, 2025).
cancer (13 papers, 2010 to 2025). A tumor composed of atypical neoplastic, often pleomorphic cells that invade other tissues. "FOXS1 has a high expression in pan-cancers, and the gene is linked to a worse surviva." (PMID 40308606, 2025). "Furthermore, FOXS1 expression regulates cancer-associated pathways and biological processes (P<0.05)." (PMID 38310407, 2023). "These opposite results suggest that the function of FOXS1 could be dependent on specific cell-specific contexts associated with different genetic/epigenetic backgrounds of cancer subtypes." (PMID 35898871, 2022). "The expression of FOXS1 in cancer samples increased considerably compared to adjacent normal samples, while the expression of CASZ1 decreased (P < 0.01)." (PMID 36344988, 2022). "In the present study, we provided evidence that FOXS1 not only promoted EMT in CRC cells but also was involved in angiogenesis in human cancers." (PMID 35898871, 2022). "Nevertheless, the role of FOXS1 in cancer remains controversial according to the results from these studies." (PMID 35898871, 2022). "Forkhead Box S1 (FOXS1), as a newly identified subfamily of the FOX family, is overexpressed in certain types of malignant tumors and closely associated with patient's prognosis." (PMID 35864528, 2022). "Overexpression of FOXS1 promotes cancer cell proliferation, invasiveness, angiogenesis, tumor growth, and metastasis." (PMID 35898871, 2022). "Additionally, the Forkhead box (FOX) family of transcription factors (FOXF1, FOXS1, FOXM1, FOXK1, FOXP4, and FOXC1) play a role in cell differentiation and proliferation and are implicated in cancer and drug resistance." (PMID 35854219, 2022). "After we identified that the expression of three FOX genes (FOXD4, FOXH1, and FOXS1) are independent prognostic factors and regulate tumor immunity in COAD, we investigated the Spearman’s correlation of these three genes with various cancer-associated pathways activity (R > 0.20 and P < 0.01)." (PMID 38310407, 2023). "The role of FOXS1 in the development and progression of human cancers is largely unknown." (PMID 35898871, 2022). "However, the expression pattern and biological function of FOXS1 in cancer are largely unknown." (PMID 35898871, 2022). "FOXS1 expression rose in TCGA and GSE39582 cancer samples, but CASZ1 expression dropped, according to the results of the preceding steps." (PMID 36344988, 2022). "Additionally, we also identified several genes, including FOXS1, FOXP3, and FOXD2, showed elevated expression in a variety of tumors, while FOXF1, FOXP2, and FOXO1 were downregulated in the majority of cancers." (PMID 37401400, 2023). "As the structure of FOXS1 is highly similar with FOXC2, we propose that they may share similarities in their biological functions in human cancers." (PMID 35898871, 2022). "Furthermore, the networks related to cell cycle, cancer and nervous system development and function showed that several genes such as Nfkb2, NFκBia, BRCA1, Vegf, Jag2, Notch1, EGR1, FoxS1 and collagen type I were regulated by TNF." (PMID 20967264, 2010). "In addition, we investigated the expression variation of these prognostic markers in cancers using the Oncomine database and GSE166427, and found consistent results which ultimately indicate the substantial roles of FOXD4, FOXH1, and FOXS1 incolon cancer." (PMID 38310407, 2023). "This phenomenon suggests that there may be negative feedback between FOXS1 and GLI1 in human cancers that needs to be further studied." (PMID 30918291, 2019).
tumor (12 papers, 2016 to 2025). "The FT FOXS1 is associated with several cell proliferation steps, and its overexpression inhibited tumor cell proliferation." (PMID 35629975, 2022). "Together, these data indicated that FOXS1 is involved in tumorigenesis and tumor metastasis in vivo." (PMID 35864528, 2022). "Subcutaneous inoculation assay showed that overexpression of FOXS1 significantly increased, while knockdown of FOXS1 significantly decreased the tumor growth in nude mice." (PMID 35898871, 2022). "To assess the effect of FOXS1 on tumor growth and metastasis in vivo, we constructed stably transfected LoVo cells for subcutaneous xenografting in nude mice." (PMID 35864528, 2022). "The overexpression of FOXS1 promotes tumor angiogenesis, invasion, and metastasis by upregulating C–X–C motif chemokine ligand 8 (CXCL8)." (PMID 35898871, 2022). "The results showed that FOXS1 overexpression increased tumor growth in terms of both size and weight in nude mice." (PMID 30918291, 2019). "We found that the FOXH1 and FOXS1 genessubstantially regulate tumor immunity in COAD." (PMID 38310407, 2023). "Furthermore, we used a mice tail vein injection model to examine the effect of FOXS1 on tumor metastasis." (PMID 35864528, 2022). "FOXS1 knockdown markedly suppressed tumor growth in vivo compared to that of the controls." (PMID 35864528, 2022). "Then, We confirmed that FOXS1 is involved in tumorigenesis and tumor metastasis in vivo." (PMID 35864528, 2022). "Additionally, tumor formation assay and orthotopic implantation assay were used to investigate the effects of FOXS1 on tumor growth and metastasis in vivo." (PMID 35898871, 2022). "FOXS1 is a novel oncogene in the regulatory network of tumour progression." (PMID 34256854, 2021). "Additionally, forced expression of FOXS1 accelerated tumor growth in vivo and increased cell migration and invasion through promoting epithelial–mesenchymal transition (EMT) both in vitro and in vivo." (PMID 30918291, 2019). "FOXS1 expression was positively related to tumor size and advanced age and could be an independent prognostic factor." (PMID 30918291, 2019). "The FOXS1/CXCL8 axis promoted tumor cell migration, invasion, angiogenesis, and metastasis in CRC, suggesting that FOXS1/CXCL8 may be a novel target in disrupting tumor-associated angiogenesis and in controlling advanced CRC." (PMID 35898871, 2022). "In addition, FOXS1 promoted tumor growth and metastasis in nude mice." (PMID 35898871, 2022). "Consequently, FOXS1 may have tumor suppressive properties and its up‐regulation in tumors could be a marker of good prognosis." (PMID 30098229, 2018). "Forkhead box S1 (FOXS1) is a member of FOX TFs that can modulate EMT and is correlated with poor prognosis of tumor." (PMID 39092293, 2024). "FOXS1 can inhibit the ubiquitination of GLI1 to upregulate Hedgehog/GLI1 signaling, which leads to tumor metastasis via inducing EMT." (PMID 39092293, 2024). "First, we found that the stromal scores, immune scores, and tumor purity are significantly deregulated (Wilcoxon sum rank test, P < 0.05) between the HEG and LEG of FOXH1 and FOXS1." (PMID 38310407, 2023). "As compared with the role of FOXS1 in EMT, the function of FOXS1 tumor angiogenesis is rarely known." (PMID 35898871, 2022). "Previous reports described that EMT is a key process involved in chemotherapeutic resistance, and a close correlation between FOXS1 and the EMT process in tumour progression has been reported; therefore, we investigated the underlying mechanism by which FOXS1 activates the EMT process." (PMID 34256854, 2021). "Since GSEAs revealed that a higher FOXS1 expression was positively correlated with the enrichment of the angiogenesis-related gene signature, we performed tube formation, HUVEC migration assay, and chicken CAM assays to validate the effect of FOXS1 on tumor cell-induced angiogenesis." (PMID 35898871, 2022).
tumor (continued). "The expression of FOXS1 protein was distributed in the cytoplasm and nucleus of CRC tumor cells but was negative in normal colonic tissue cells." (PMID 35864528, 2022).
FOXS1 also shares sentences with these, for which no sentence is quoted: colon cancer (2 papers); aortic valve calcification (1); glioblastoma (1); Insulin resistance (1); lung carcinoma (1); rhabdomyosarcoma (1); triple-negative breast carcinoma (1).